TREM1 (triggering receptor expressed on myeloid cells 1)
Diseases named in the same sentence as TREM1 in open-access papers (continued):
Sharing a sentence is not in itself a finding about the gene and the disease.
tumor (continued). "Increase in CD68 positive macrophages in our study supports the hypothesis that inflammatory macrophages expressing TREM-1 may contribute to continued production of mediators which may promote tumor growth." (PMID 24842612, 2014). "Most recently, we found TREM-1 was a pro-tumor gene in HSCs, however, two independent studies on human gene expression profile displayed its contradictory roles in development of T cells: enhancing Th1 priming in mature dendritic cells and dampening Th1 and Th17 responses in monocytes." (PMID 23305119, 2013). "TREM1 expression in macrophages is also regulated by NF-κB at the transcriptional level again emphasizing the contribution of NF-κB pathway activation in bridging inflammation and tumor promotion and progression." (PMID 19536297, 2009). "Finally, examining TREM1’s role across additional tumor types may broaden its utility as a cancer stem cell–directed therapeutic target." (PMID 40677705, 2025). "Therefore, simultaneously targeting CD46 and TREM1 may yield synergistic effects, more effectively blocking tumor immune evasion mechanisms and enhancing the body’s antitumor immune response." (PMID 41415031, 2025). "Therefore, we hypothesize that activation of myeloid cells through TREM-1 may establish a permissive microenvironment that enables CD8+ T cells to exert anti-tumor effector functions." (PMID 40917508, 2025). "Additionally, in a mouse xenograft NSCLC model, TREM1 inhibition suppressed NSCLC tumor growth." (PMID 39149674, 2024). "Hence, TREM-1 might play a critical role in regulating the tumor microenvironment in ccRCC and may influence the prognosis of patients." (PMID 37217993, 2023). "Additionally, to comprehensively characterize the impact of TREM1 deficiency specifically within the tumor myeloid populations, we selectively enriched the CD45+CD11b+ tumor–infiltrating myeloid cells from tumor-bearing Trem1+/+ and Trem1–/– mice for scRNA-Seq analysis." (PMID 37651197, 2023). "TREM-1 paracrine signaling may also activate tumor-intrinsic pathways." (PMID 34956864, 2021). "Furthermore, they found a correlation of TREM-1 expression with tumor recurrence and bad prognosis." (PMID 32684831, 2020). "Therefore, we suspect that increased TREM1 may play a role in promoting tumor migration and angiogenesis through the release of certain inflammatory factors." (PMID 32765489, 2020). "Thus, TREM-1 is positively correlated with anti-tumor function of NK cells." (PMID 31275318, 2019). "In addition, tumor cells can promote the up-regulation of TREM-1 expression on TAM in tumor environment, suggesting that TREM-1 could boost carcinogenesis and cancer progression with an unknown mechanism." (PMID 27244892, 2016). "Also, the effect of T-bet on TREM-1 expression was further confirmed in tumor microenvironment, indicating that T-bet might be essential for the increase the TREM-1 expression on monocyte/macrophage." (PMID 27244892, 2016). "Therefore, all these evidences indicated that the expression and functions of TREM-1 might be different between pathogen infection status and tumor-bearing status." (PMID 27244892, 2016). "Therefore, our findings suggested that the inherent function of TREM-1 might still work as an amplifier of immune responses in tumor microenvironment, but its effects will be gradually receded with the decrease of TREM-1 levels on TAM with tumor progression." (PMID 27244892, 2016). "However, the role of TREM-1 in tumor associated inflammation and microenvironment has not been established." (PMID 24842612, 2014). "Myeloid and dendritic cell functionality was analyzed following treatment with different compounds (TLR agonists, TREM1 agonist, STING agonist, or T-cell engagers) and following the implantation of different tumor cell lines (MDA-MB-231, A549, HPAF-II)." (PMID 41041306, 2025).
tumor (continued). "While the Triggering Receptor Expressed on Myeloid Cells 1 (TREM1) is well-known for its role in amplifying inflammation within the tumor microenvironment (TME), its tumor-intrinsic role remains poorly defined." (PMID 40677705, 2025). "Collectively, our study revealed the conserved immunosuppressive features and spatial interaction networks of TREM1+ PMN-MDSCs from a pan-cancer perspective, highlighting TREM1 as a pivotal therapeutic target to disrupt PMN-MDSC-mediated tumor immune evasion." (PMID 41413734, 2025). "LP17-mediated TREM1 inhibition attenuated PMT through modulation of the TLR4/PI3K/AKT/mTOR pathway and reduced tumor growth in vivo." (PMID 41394801, 2025). "We show that TREM-1 activation reprograms myeloid cells in the TME of PDAC toward an immunostimulatory phenotype, resulting in increased tumor-infiltrating lymphocyte activation and enhanced killing of tumor cells, thereby reducing tumor growth." (PMID 40917508, 2025). "This suggests that TREM1, in concert with AKT signaling, plays a significant role in maintaining a pro-tumor TAM phenotype." (PMID 40764998, 2025). "In this study, we present TREM-1 activation as an effective treatment strategy to reprogram myeloid cells into a proinflammatory phenotype in PDAC and to promote tumor specific immune responses." (PMID 40917508, 2025). "In vivo experiments showed that the tumor volume of the shRNA group was significantly smaller than that of the SC-shRNA group (P<0.01), the expression of CD46 and TREM1 was decreased considerably, and the expression of LC3B and ATG5 was higher (P<0.01)." (PMID 40475017, 2025). "Subsequent analyses identified TREM1 as a pivotal functional regulator in PMN-MDSCs, which was highly expressed in various tumor tissues, and elevated TREM1 expression was significantly correlated with poor prognosis." (PMID 41413734, 2025). "In vivo inhibition of TREM1 with LP17 likewise resulted in attenuated tumor growth and enhanced tumor cell apoptosis." (PMID 41394801, 2025). "A co-culture system demonstrated TREM1’s influence on GBM cell malignancy and PMT progression in vitro, while intraperitoneal LP17 administration assessed its impact on tumor growth." (PMID 41394801, 2025). "This study explores the potential of triggering receptor expressed on myeloid cells 1 (TREM-1) activation in altering the TME and enhancing tumor immunity in PDAC." (PMID 40917508, 2025). "Through both genetic and pharmacological approaches, we demonstrate that TREM1 supports LCSLC proliferation, self-renewal, and tumor-initiating capacity via context-specific transcriptional programs." (PMID 40677705, 2025). "Importantly, unlike the TREM2 myeloid cell signature, the 16-gene BIT-associated TREM1 myeloid signature was specifically enriched in BIT regions spatially, reinforcing the spatial association between BIT tumor epithelium and the specialized TREM1 myeloid cell-associated inflammatory environment." (PMID 39289380, 2024). "We reasoned that TREM1, inflammation and IL1/OSM expression would correlate with abundance of BIT tumor epithelium." (PMID 39289380, 2024). "To understand the tumor-promoting effect of TREM1 in HCC, we explored the relationship between TREM1 expression and immune infiltration in HCC." (PMID 38914803, 2024). "We show that TREM1 myeloid-derived cytokines IL1 and OSM activate the inflammatory NF-κB family of transcription factors within the BIT tumor epithelium and lower the sensitivity of human BCC explant tumors to SMOi treatment, conferring resistance." (PMID 39289380, 2024). "A screen of signaling patterns predicted strong signaling interactions between TREM1 myeloid cells and BIT tumor epithelium, with candidate TREM1 myeloid cell-derived signals including EGF, VISFATIN, IL1, TGF-β, and OSM." (PMID 39289380, 2024).
tumor (continued). "Interestingly, several representative genes of tumor-associated neutrophils were highly expressed in OtoNP+ group, including OSM and TREM1, which further suggest that neutrophils might participate in shaping the tumor immune microenvironment by intratumoral translocated microbes." (PMID 38388556, 2024). "The observed increase in the TREM-1/TREM-2 (%, MFI) ratio and decreased TREM-2 MFI expression indicates a shift toward more pro-inflammatory and tumour-promoting conditions, as demonstrated in patients versus healthy controls (p ≤ 0.001, p = 0.004)." (PMID 39684475, 2024). "To gain a global understanding of the impact of TREM1 silencing, we analyzed the CD45+ tumor-infiltrating cells (TICs) of B16F10 tumor-bearing Trem1+/+ and Trem1–/– mice." (PMID 37651197, 2023). "In the current study, combining TREM1 inhibition and anti-PD-1 ICB induced complete tumor regression." (PMID 37651197, 2023). "We have recently shown that the ligand of the innate immunity receptor TREM-1, the Tag7 protein, not only enhances inflammatory processes, but also activates the generation of CD8+ T lymphocytes that kill MHC-negative tumor cells." (PMID 36653582, 2023). "Our findings reveal a role of TREM1 in promoting tumor-intrinsic oncogenic pathways and MDSC tumor-infiltration, thus contributing strongly to an immunosuppressive state." (PMID 37651197, 2023). "Myeloid phenotypes with the highest fold changes between densely packed tumor cells and necrotic and perivascular areas were CD206+/CD14+/CD64+ (FC.404), CD206+/CD14+/CD64- (FC3.09), and TREM1+ (FC3.62)." (PMID 37694144, 2023). "Here, we show that TREM1 modulates TME and MDSC functions, acts as a tumor oncoprotein, and is a potential cancer therapeutic target." (PMID 37651197, 2023). "We also identified unique signatures in tumour samples after VV-αCEA TCE treatment, including increased levels of CCL1, IFNγ, IL-1a, IL-1b, TIMP-1, and TREM-1." (PMID 36405739, 2022). "These scores all increased in high-expression group of COLEC12, TREM1 and S100A9, while the corresponding tumor purity decreased, which further confirmed the roles of these IRGs in regulating tumor microenvironment." (PMID 36685822, 2022). "Through multidimensional analysis, we evaluated the genomic functional networks related to TREM-1 in PTC and further explored the role of TREM-1 in tumor immunity." (PMID 34122331, 2021). "In this study, we found that both TREM-1 and TREM-2 were expressed on MDSC and TAM and that tumor-bearing mice have elevated levels of sTREM-1 in their blood." (PMID 35223446, 2021). "We have shown previously that the innate immunity protein Tag7 (PGLYRP1), recently described as a ligand for TREM-1, also induces activation of cytotoxic lymphocytes that kill MHC-negative tumor cells." (PMID 34206968, 2021). "Overall, TREM-1 is expressed in tumor-infiltrating MDSC and is notably upregulated in PMN-MDSC during tumor progression." (PMID 35223446, 2021). "To further investigate the relationship between TREM1 and tumor infiltrating immune cells, we used the CIBERSORT algorithm to study the relationship between immune cell abundance estimates and TREM1 expression quartiles in the MC1 cohort." (PMID 34956864, 2021). "Consistent with our mRNA analysis, TREM-1 was expressed on tumor-infiltrating PMN-MDSC, Mo-MDSC, and TAM in all three tumor models." (PMID 35223446, 2021). "In NSCLC, TREM-1 expression in tumors was restricted to tumor-infiltrating CD68+ myeloid cells, yet soluble TREM-1 in serum was also reported to have prognostic significance." (PMID 34956864, 2021). "Thus, we propose that TREM-1 may serve as a biomarker for tumor progression and a useful target for reprogramming the immunosuppressive tumor microenvironment of the host and that TREM2 might play an important role in balancing the inflammatory signals within the tumor." (PMID 35223446, 2021). "Moreover, TREM-1+ monocytes could enter into the tumor and promote its growth." (PMID 32684831, 2020).
tumor (continued). "To investigate the effect of TREM1 on tumor growth in vivo, we treated mice bearing orthotopic GBM xenograft with peptides as a control and with LP17, which blocks TREM1." (PMID 32765489, 2020). "According to fold changes of expression level between non-tumor and tumor, representative target genes were CLIP2, TREM1 (miR-26a), SPOCK1 (miR-375), PENK, and ADAMTS16 (miR-1260)." (PMID 32313120, 2020). "Owning to the complexity of HCC, there are still many issues regarding the function and mechanism of TREM1 and TREM2 that need to be further studied, including the role of the gene and the tumor microenvironment." (PMID 33297569, 2020). "In contrast to tumor-infiltrating APCs, pathways related to the positive regulation of immune and defense response, including IL-8/IL-6/IL-3/CXCR4 signaling, TREM1 signaling and leukocyte extravasation pathways were downregulated in I-MDSCs." (PMID 33312958, 2020). "Western blot and immunohistochemistry analysis demonstrated that TREM-1 is up-regulated in ApoE KO mice in both urethane-induced lung tumor and B16F10 lung metastasis tumor tissues." (PMID 31275318, 2019). "We observed up-regulation (more than 2 standard deviations) of number of pro-inflammatory cytokines (G-CSF, GM-CSF, IFN-γ, IL-1β, IL-17, TREM-1, TNF) in mice with three-week tumors as compared to one-week tumor." (PMID 30323345, 2018). "The expression pattern of TREM1 was closely paralleled by the expression of IL1B and S100A9 which were also increased in the tumor tissue." (PMID 29093489, 2017). "In summary, we found the different pattern of TREM-1 expression from previous reports in patients with NSCLC and tumor-bearing mouse model." (PMID 27244892, 2016). "However, recent studies demonstrated that TREM-1 might be involved in tumor progress." (PMID 27244892, 2016). "However, recent studies indicated that TREM-1 could promote tumor progression." (PMID 27244892, 2016). "To investigate the expression feature of TREM-1 on TAM in tumor microenvironment, we detected the levels of TREM in tumor tissues and distal normal lung tissues with flow cytometry." (PMID 27244892, 2016). "Our data suggest that expression of COX-2 in tumor cells leads to production of PGE2 which through EP2 and EP4 receptors leads to induction of TREM-1." (PMID 24842612, 2014). "The expression of TREM-1 in tumor microenvironment is dependent on the cyclo-oxygenase pathway and is mediated by increased production of PGE2.by tumor cells." (PMID 24842612, 2014). "Whereas in tumor-bearing mice groups, most of cytokines were decreased after LF-MF exposure, including KC, CCL1, IFN-γ, CXCL9, CXCL12, TREM-1, CCL12, IL-1rα and IL-16." (PMID 24314291, 2013). "Moreover, it drives the secretion of TREM1-enriched extracellular vesicles that activate microglia via the Akt-ERK1/2-STAT3 axis, thus remodeling the tumor immune microenvironment and promoting tumor progression." (PMID 41583444, 2025). "Importantly, our experiment confirmed that TREM1+ PMN-MDSCs were induced and expanded within tumor tissues." (PMID 41413734, 2025). "Additionally, hypoxia-induced TREM-1 expression in TAMs exacerbates immunosuppression in advanced HCC, impairing T cell cytotoxicity and facilitating tumor progression." (PMID 40764998, 2025). "However, spatial transcriptomics allowed us to specifically map TREM1 expression and identify its cellular localization and proximity to the CD8+ T cells and tumor regions." (PMID 40917508, 2025). "By targeting TREM1, it may be possible to simultaneously impair LCSLC-driven tumor progression and enhance antitumor immunity." (PMID 40677705, 2025). "Using the Pan02 mouse model and single-cell RNA sequencing (scRNA-seq), we found that intra-tumoral TREM-1 activation significantly reduced Pan02 tumor growth, an effect absent in Trem1−/− mice." (PMID 40917508, 2025). "Multiplex immunofluorescence demonstrated that TREM1+ PMN-MDSCs exhibited significantly higher distribution in tumor regions compared to non-tumor tissues." (PMID 41413734, 2025).
tumor (continued). "The beneficial effect of TREM-1 activation on tumor growth was abrogated with either treatment in the absence of TREM-1, confirming that the decrease in tumor volume is TREM-1 specific." (PMID 40917508, 2025). "It has also been demonstrated that macrophages expressing TREM1 are important in the progression of HPV+ OPSCC and that fibroblasts with a matrix-CAF phenotype collaborate with SPP1-expressing TAMs to promote tumour progression in HNSCC." (PMID 38803348, 2024). "Genetic silencing of TREM1 or its pharmacological inhibition using the newly developed inhibitor VJDT restrains tumor growth, and, in combination with anti-PD-1 treatment, results in complete tumor regression." (PMID 37651197, 2023). "Single-cell RNA-Seq (scRNA-Seq) combined with functional assays of Trem1–/– tumor infiltrates revealed, in the absence of TREM1 signaling, a decreased immunosuppressive capacity of MDSCs and increased PD-1 expression on CD8+ T cells." (PMID 37651197, 2023). "We hypothesized that TREM-1 and TREM-2 might be co-expressed on tumor-infiltrating myeloid cells and that elevated sTREM-1 associates with disease outcomes, thus representing a possibility for mutual modulation in cancer." (PMID 35223446, 2021). "A plausible explanation is that these anti-inflammatory factors are not direct targets of TREM-1, or are not solely modulated by TREM-1, and therefore, are likely not major contributors to TREM-1-related tumor phenotypes." (PMID 34956864, 2021). "Unfortunately, the recent TREM-2 studies did not assess systemic soluble TREM-1, nor did it assess the total tumor levels of the receptors." (PMID 35223446, 2021). "Therefore, we sought to assess TREM-1 expression on CD14+ monocytes and on neutrophils in peripheral blood and/or tumor tissues of patients with RCC." (PMID 35223446, 2021). "Thus, TAM and Mo-MDSC are the most likely sources of Trem2 within the tumor, whereas PMN-MDSC and TAM are the primary sources of Trem1." (PMID 35223446, 2021). "Therefore, we examined the expression of ligands for TREM-1 and TREM-2 on tumor-infiltrating myeloid cells using TREM/Fc chimeras." (PMID 35223446, 2021). "While TREM-1 engagement enhanced TNF, a TREM-2 ligand was detected on MDSC and TAM, suggesting that both TREM could be functional in the tumor setting." (PMID 35223446, 2021). "In another study in NSCLC, TREM-1 expression was shown to be induced in TAMs by tumour cell mediated prostaglandine-2 (PGE2) production, suggesting a link between the tumour cell derived cyclo-oxygenase 2 (COX-2) pathway and the expression of TREM-1 in TAMs58." (PMID 32908142, 2020). "An additional level of complexity is given by the evidence of TREM-1 expression on other myeloid and non-myeloid cells involved in anti-tumor responses." (PMID 32456204, 2020). "In 6/8 cases analyzed, increased mRNA for TREM-1 was indeed detected in the tumor as opposed to the non-tumor tissue." (PMID 29093489, 2017). "Trem1−/− and Trem1+/+ mice were injected twice with the procarcinogen AOM and subjected to three cycles of DSS administration, followed by an additional latency period to allow for visible tumor growth." (PMID 29093489, 2017). "As seen for inflammatory genes such as Il1b and Il6, also the expression of Trem1 was highly increased in Trem1+/+ tumors as opposed to matched tumor-free colonic mucosa." (PMID 29093489, 2017). "The levels of TREM-1 on tissue-infiltrating monocytes/macrophage from tumor nest were significantly lower than those from nonturmor tissue or peripheral blood samples." (PMID 27244892, 2016). "In this study, we examined the expression of TREM-1 on blood monocytes, tumor and corresponding nontumor tissue-filtrating macrophage in patients with NSCLC." (PMID 27244892, 2016). "We were not able to detect the expression of TREM-1 message or protein in tumor cells alone (data not shown)." (PMID 24842612, 2014). "We were not able to detect the expression of TREM-1 in normal lung tissue or in isolated tumor cells." (PMID 24842612, 2014).